WWP2 (WW domain containing E3 ubiquitin protein ligase 2)
Diseases named in the same sentence as WWP2 in open-access papers (continued):
Sharing a sentence is not in itself a finding about the gene and the disease.
tumor (28 papers, 2014 to 2026). "In this study, we found that WWP2 expression is significantly increased in GC tumor tissues and that overexpression of WWP2 is associated with malignant phenotypes." (PMID 36803368, 2023). "The HECT-domain containing WWP2 E3 ligase ubiquitinates many proteins and has been implicated in regulating the activity of tumor promoters and suppressors in different cancer types." (PMID 29954076, 2018). "This functional interplay was corroborated in vivo, as WWP2 depletion enhanced tumor cell senescence and suppressed tumor growth, an effect that was partially rescued by concurrent CMTM6 knockdown." (PMID 41387673, 2025). "The E3 ubiquitin ligase WWP2 has emerged as a critical regulator of tumor pathogenesis through its modulation of substrate ubiquitination." (PMID 41387673, 2025). "In vivo experiments demonstrated that WWP2 knockdown led to increased tumor cell senescence and suppression of tumor growth." (PMID 41387673, 2025). "Western blot and immunohistochemical analysis revealed significantly elevated WWP2 protein levels in tumor tissues compared with matched normal tissues." (PMID 41387673, 2025). "Conversely, WWP2 suppresses tumor-initiating cell activity by degrading the pluripotency factor OCT4, delaying HCC progression." (PMID 41387673, 2025). "To comprehensively investigate the expression profile of WWP2, first, we analyzed its expression levels across 33 tumor types using the TCGA database." (PMID 41387673, 2025). "Subsequently, we further compared WWP2 expression between 23 tumor tissues and their paired normal tissues." (PMID 41387673, 2025). "To clinically validate WWP2 expression patterns, we analyzed 30 paired tumor and adjacent normal tissues from HCC patients." (PMID 41387673, 2025). "The results demonstrated that WWP2 expression was significantly elevated in four tumor types (CHOL, LIHC, PRAD, and STAD) compared with their adjacent normal tissues." (PMID 41387673, 2025). "Then, a radar plot was generated to display the distribution patterns and statistical differences of WWP2 expression across multiple tumor tissues and adjacent normal tissues." (PMID 41387673, 2025). "Taken together, WWP2 knockdown suppresses HCC tumor growth and promotes senescence in vivo, and these effects are abrogated by CMTM6 knockdown, confirming our cellular findings." (PMID 41387673, 2025). "WWP2 overexpression restricts MM tumor growth and enhances cell sensitivity to bortezomib treatment in vitro and in vivo." (PMID 40809696, 2025). "TMEM127 interacts with an endogenous transmembrane protein, SUSD6, and WWP2 to mediate the reduction of MHCI in tumour cells." (PMID 41135677, 2025). "Intriguingly, WWP2 exhibits a dual role as both an oncogene and tumor suppressor in HCC through substrate-specific modulation mechanisms." (PMID 41387673, 2025). "Previous studies have shown that WWP2 exhibits either oncogenic or tumor-suppressive effects depending on its regulated substrates in tumors." (PMID 41387673, 2025). "Consistently, WWP2 upregulation was dramatically associated with TNM stage (p = 0.009), lymphatic metastasis status (P = 0.031) and depth of tumor invasion (p = 0.007) in GC patients." (PMID 36803368, 2023). "Consistently, WWP2 knockdown resulted in a significant reduction in xenograft tumor volume and weight." (PMID 36803368, 2023). "GC cells that expressed WWP2 shRNA or scramble shRNA were inoculated into the right armpit of nude mice, and xenograft tumor size was monitored for 25 days." (PMID 36803368, 2023). "It indicated that Dox intraperitoneal injection inhibited tumor growing obviously and knockout WWP2 inhibited the growth of ALL xenograft tumor under both normal conditions and Dox stimulation." (PMID 36257929, 2022). "Then we gave intraperitoneal injection of normal saline (NS) or Dox randomly in each group, aiming to evaluate WWP2 function to tumor growth under the stimulation of Dox." (PMID 36257929, 2022).
tumor (continued). "WWP2, like WWP1, has been associated with a number of different cancers, acting as either an oncogene or as a tumour suppressor in different cell contexts." (PMID 35204725, 2022). "WWP2 is involved in the regulation of tumor progression by interacting with and degrading p27 and PTEN, in which WWP2 functions as a tumor-promoting factor." (PMID 35983977, 2022). "WWP2 (WW domain containing E3 ubiquitin protein ligase 2) gene encodes a protein that play a role in the regulation of oncogene signaling pathways via interactions with SMAD proteins and the tumor suppressor PTEN." (PMID 35178295, 2022). "Initially, WWP2 was considered a tumour‐promoting factor involved in the development of tumours by regulating PETN and Smad." (PMID 32627301, 2020). "WWP2 is an E3 ubiquitin ligase that differentially regulates the contextual tumour suppressor/progressor TGFβ signalling pathway by alternate isoform expression." (PMID 31546607, 2019). "Here we report that in various tumor cells, Cdh1, conversely, suppresses the E3 ligase activity of WWP2, another NEDD4 family protein, in an anaphase-promoting complex/cyclosome-independent manner." (PMID 27462441, 2016). "Tumor weight measured at the endpoint of the study was also significantly lower in the WWP2-expressing group than in the control group." (PMID 25356737, 2014). "We observed that WWP2 expression led to a significant reduction in tumor formation and in fact as compared to the control group, tumors in the WWP2 expressing group were hardly detectable." (PMID 25356737, 2014). "The result indicated that ovarian HGSC tissues and primary tumor cell cultures with higher Notch3 expression levels tended to have lower expression levels of WWP2, and vice versa." (PMID 25356737, 2014). "Substantial evidence indicates that WWP2 predominantly functions as an oncogenic driver, yet may exert tumor-suppressive effects under specific conditions." (PMID 41387673, 2025). "Similarly, tumor growth curves demonstrated that WWP2 knockdown markedly suppressed tumor growth, which was also rescued by CMTM6 knockdown." (PMID 41387673, 2025). "In addition, tumor tissues were stained with H&E to observe tumor cell morphology, and immunohistochemistry (IHC) was performed to detect the expression level of p21, WWP2, CMTM6, the cell cycle promoter c-MYC, and the proliferation marker PCNA." (PMID 41387673, 2025). "Therapeutic strategies targeting WWP2 may require substrate-specific approaches: inhibiting oncogenic substrates while activating tumor-suppressive ones." (PMID 41387673, 2025). "Since LATS1 is a tumor suppressor in GC, targeting its upstream regulators, such as WWP2, to increase LATS1 expression could be an ideal therapeutic strategy." (PMID 36803368, 2023). "We established xenograft tumor model in order to investigate the WWP2 function in tumor growth." (PMID 36257929, 2022). "It indicated that knockout WWP2 enhanced apoptosis of ALL tumor cells induced by Dox in vivo." (PMID 36257929, 2022). "WWP2 accelerates the cell cycle and promotes tumor formation." (PMID 36211818, 2022). "Next, we tested if TRIM26 and WWP2 control SOX2 protein levels in tumor cells in vivo." (PMID 34732716, 2021). "Given the critical role of SOX2 in GSC self-renewal and tumor formation, we hypothesized that WWP2 knockdown might promote these GSC phenotypes." (PMID 34732716, 2021). "Finally, we asked if the TRIM26/WWP2 ubiquitin signaling pathway is relevant for in vivo GBM tumor formation in GSC-based mouse models." (PMID 34732716, 2021). "In contrast, mice injected with WWP2 knockdown GSCs showed a high number of tumor cells." (PMID 34732716, 2021). "To determine whether WWP2 expression affects tumor development, we ectopically expressed WWP2 in SKOV3-CR cells which were pre-established to develop carboplatin resistance (CR) phenotype and expressed abundant Notch3." (PMID 25356737, 2014).
tumor (continued). "Hence, our current study revealing tumor suppressor p73 as an additional functional downstream substrate of WWP2 E3 ligase activity certainly provided important evidence in understanding the role of this E3 ligase as a potential oncogene." (PMID 25071155, 2014). "Furthermore, WWP2 silencing attenuated tumor growth by regulating the Hippo-YAP1 pathway in vivo." (PMID 36803368, 2023). "Here, through a genome-wide mutant screen of human antigen-presenting cells, we show that the NEDD4 family HECT E3 ubiquitin ligase WWP2 and a tumor-suppressing transmembrane protein of unknown biochemical function, TMEM127, are required for SteD-dependent ubiquitination of mMHCII." (PMID 32526160, 2020). "Our in vitro and in vivo experiments confirmed that WWP2 knockdown promotes cellular senescence and suppresses HCC proliferation, aligning with its tumor-promoting role." (PMID 41387673, 2025). "Based on the in vitro data above, we further investigated the role of WWP2 and CMTM6 via xenograft tumor models in vivo." (PMID 41387673, 2025). "There are direct pieces of evidence illuminating the oncogenic and tumor-suppressive roles of WWP1 and WWP2." (PMID 37568787, 2023). "And subsequent experiment proved that knockout WWP2 inhibit growth and aggravated apoptosis in ALL xenograft tumor." (PMID 36257929, 2022). "Emerging evidence indicates that WWP2 overexpression suppresses TLR3-mediated immune response, which may facilitate tumor immune evasion." (PMID 40809696, 2025). "Notably, a previous study demonstrated that WWP2 exhibits dual roles in HCC, acting as both an oncogene and a tumor suppressor." (PMID 41387673, 2025). "However, depletion of WWP2 decreased cell growth, blocked PI3K/AKT signaling, increased PTEN expression, promoted cell cycle arrest, and inhibited tumor growth in vivo." (PMID 29954076, 2018). "Since we determined that PPM1G positively regulates p73 levels and negatively regulates its counterpart ΔNp73 by controlling WWP2, it is tempting to speculate that PPM1G might act as a potential tumor suppressor." (PMID 25071155, 2014). "As a result, unlike NEDD4-1 or WWP2, FBXO22 did not affect AKT activation, but negatively regulated nuclear PTEN functions, such as the activity of APC/C-CDH1 complex and alternative splicing, to play a tumor-promoting role." (PMID 32249768, 2020).
infection (5 papers, 2019 to 2024). The state of being infected such as from the introduction of a foreign agent such as serum, vaccine, antigenic substance or organism. "As many RNA viruses are already known to recruit proteins from the Nedd4 family, including ITCH, to facilitate budding, we investigated the role of ITCH, WWP1 and its homolog WWP2 during infection by various old-world arenaviruses." (PMID 31906112, 2019). "Here we demonstrated that WWP1, WWP2, and NEDD4 are overexpressed during SARS-CoV-2 infection and that their expression co-localizes with areas of infection in lung tissue both in mice and humans." (PMID 33762578, 2021). "Here, we also observed substantial increases in the mRNA expression of different HECT E3 ligases, specifically WWP1, WWP2, SMURF1 and NEDD4, in infected Vero E6 and Calu-3a cells, which could exacerbate infection." (PMID 36754974, 2023). "Although not statistically significant, the depletion of WWP1 and WWP2 moderately decreased infectious particles production for all assessed infections." (PMID 31906112, 2019). "Activation of wild-type MutuDCs by infection with steD mutant Salmonella led to significantly higher surface MHCII levels than DCs that were not exposed to bacteria, and these levels were unaffected by the absence of either Wwp2 or Tmem127." (PMID 32526160, 2020).
cardiovascular diseases (4 papers, 2020 to 2024). "In addition, the roles of WWP2 in other cardiovascular diseases and whether WWP2 has functions in patients with hypertensive angiopathy should be further assessed." (PMID 32627301, 2020).
heart disease (4 papers, 2019 to 2022). "WWP2 mRNA expression was only marginally increased the fibrotic heart disease (less than 2 folds in either human DCM, rTOF, or mouse HF30)." (PMID 31399586, 2019). "This regulatory SNP (rs9936589) and WWP2 have not been previously associated with any fibrotic or heart disease." (PMID 31399586, 2019). "Therefore, WWP2, as a new drug target, is of great significance to control pathological cardiac fibrosis and heart failure, and to improve the clinical prognosis of patients with heart disease." (PMID 33110392, 2020). "Therefore, we investigated whether the WWP2 gene was a potential regulator of the hECM network in human fibrotic heart disease." (PMID 31399586, 2019). "Among the nine members of the NEDD4 family, NEDD4-1, NEDD4L, ITCH, WWP1, WWP2, SMURF1 and SMURF2 are involved in heart diseases." (PMID 33110392, 2020).
adenocarcinoma (1 paper, 2019). A common cancer characterized by the presence of malignant glandular cells. "A total of 72 h after transfection of the siRNA, human adenocarcinoma alveolar basal epithelial (A549) cells were efficiently depleted for ITCH, WWP1 or WWP2, as compared to cells transfected with a non-targeting (NT) control siRNA." (PMID 31906112, 2019).
genetic disorder (1 paper, 2024). "The last variant was found in WW Domain containing E3 Ubiquitin protein ligase 2 gene (WWP2), a gene that was not previously associated with a genetic disorder." (PMID 38730242, 2024).
kidney disease (1 paper, 2024). "The tubulointerstitial expression of WWP2 was associated with fibrotic progression in patients with CKD and in murine kidney disease models." (PMID 38502123, 2024). "We used kidney samples from patients with CKD and WWP2-null kidney disease mice models and leveraged single-cell RNA sequencing analysis to detail the cell-specific regulation of WWP2 in fibrotic kidneys." (PMID 38502123, 2024).
WWP2 also shares sentences with these, for which no sentence is quoted: diabetes (2 papers); oral cancer (2); acute lymphoblastic leukemia (1); arbovirus infection (1); cholangiocarcinoma (1); diabetic cardiomyopathy (1); Ebola (1); fibroid (1); gout (1); hematological disorders (1); Intervertebral Disc Degeneration (1); lobular carcinomas (1); myocardial infarction (1); polycystic ovary syndrome (1); pulmonary hypertension (1); Renal insufficiency (1); rheumatoid arthritis (1); sarcopenia (1); stomach adenocarcinoma (1); Stroke (1).